IL2 (interleukin 2)
Diseases named in the same sentence as IL2 in open-access papers (continued):
Sharing a sentence is not in itself a finding about the gene and the disease.
breast carcinoma (continued). "This indicates that JCHAIN may inhibit the proliferation and migration of breast cancer cells by affecting IL-2 and STAT4." (PMID 41010015, 2025). "Furthermore, we employed active immunotherapy using engineered small extracellular vesicles from dendritic cells (DCs) as a tumor vaccine (IL2-ep13nsEV) in combination with macbecin II for personalized breast cancer treatment." (PMID 40087501, 2025). "At the same time, cell experiments found that JCHAIN may inhibit breast cancer cell proliferation, migration, and invasion through IL-2/STAT4." (PMID 41010015, 2025). "Furthermore, the expanded T-cell population in the lungs of mammary tumour-bearing Upp1 knockout mice express IL-2, a cytokine that actively promotes T-cell proliferation." (PMID 40702342, 2025). "Taken together, these data suggest that the increased numbers of IL-2+ CD8+ T cells in the lungs of mammary tumour-bearing Upp1−/− mice may be accounted for by the reduced ability of neutrophils from MMTV-PyMT Upp1−/− mice to suppress T-cell proliferation." (PMID 40702342, 2025). "Furthermore, we know that IL-12 and IL-2 can increase IFN-γ levels in mice with HER2+ breast cancer." (PMID 37190205, 2023). "Likewise, injection of allogeneic fibroblasts transduced to secrete IL-2 or GM-CSF intratumorally into intracerebral breast cancer tumors improved survival over controls." (PMID 37046612, 2023). "In the previous years, mostly in the nineties and early two thousand, a few investigational attempts of immunotherapy in advanced breast cancer, including the ER+ subtype, were carried out based on the use of cytokines, mainly interleukin-2 or interferons alone or with anti-oestrogens." (PMID 38332913, 2023). "Thus, in breast cancer, IL-2 plays an anti-tumor effect due to increased recruitment of IL-2-releasing NK cells and the induction of anti-apoptotic function in CD8+ T cells, the main effector of the antitumor response." (PMID 36835413, 2023). "Furthermore, this research found that IL-2 treatment in a mouse model of breast cancer reduced tumor growth and metastasis, underscoring the potential for NK cell-based immunotherapies." (PMID 37516849, 2023). "The correlation analysis of TCGA-BRCA (breast cancer) revealed several inflammatory pathways associated with increased tumor NOS2/COX2 expression that influenced clinical outcomes, including the antitumor-associated IFNγ, TNFα, IL2, IL1, and IL17 pathways." (PMID 37169743, 2023). "Thus, in many cancers such as breast cancer, cytokines including leptin, IL-1B, IL-6, IL-8, IL-23, IL-17, and IL-10 stimulate while others including IL-2, IL-12, and IFN-γ, inhibit cancer proliferation and/or invasion and enhance the body’s anti-tumor defense." (PMID 36835413, 2023). "CD4+T cells could increase the secretion of IL4, IL2 promoting breast cancer progression, and the mature dendritic cells induced the proliferation of CD4+T cells." (PMID 36644231, 2023). "Besides, some further experimental studies conducted in human breast cancer cell lines provided the grounds to combine anti-oestrogens with immune therapies, including interleukin-2 in breast cancer patients." (PMID 38332913, 2023). "Moreover, PDPN-positive CAFs were associated with low IL-2 activity and resistance to trastuzumab in HER2-positive breast cancer patients." (PMID 37894446, 2023). "Treatment with TS/A (murine mammary carcinoma cells) exosomes were also shown to significantly inhibit the release of IFN-γ in IL-2-stimulated NK cells, suggesting that tumor exosomes could impair production of cytokines by activated NK cells." (PMID 35031075, 2022). "In breast cancer, IL-2 produced by myofibroblasts would promote post-radiation fibrosis." (PMID 35585990, 2022). "The two cytokines, IL-2 and IL-17, which we focused on in this study, play different roles in breast and gastric cancers, where they promote the development of gastric cancer but inhibit the progression of breast cancer." (PMID 35493488, 2022).
breast carcinoma (continued). "Together, this limited data suggests that intralesional IL-2 and imiquimod may be considered as a safe option when treating a patient with cutaneous breast cancer metastases." (PMID 35712509, 2022). "In breast cancer, high expression levels of IL-17 and IL-2 indicated a promising prognosis." (PMID 35493488, 2022). "In addition, high expression of IL-2 indicated a better prognosis in patients with ER- or HER2- breast cancer than low expression did." (PMID 35493488, 2022). "Subsequent results showed that not only TS/A exosomes but also exosomes from MDA231 (human breast cancer), A2058 (human melanoma), and the 4 T.1 (murine breast cancer) cell lines could significantly block the proliferation of NK cells induced by IL-2." (PMID 35031075, 2022). "Consequently, we investigated the effects of IL-17 and IL-2 on gastric and breast cancer, and identified their distinct roles in different malignancies." (PMID 35493488, 2022). "Furthermore, based on our investigation of the role of IL-17 and IL-2 in the prognosis of gastric and breast cancer, we discovered that they play different roles in various malignancies." (PMID 35493488, 2022). "Statistical parameters determined (absolute count, proportion, intensity and overall scores) indicated significant increase (p<0.05) in the number of CD4+ (T helper cells), CD8+ (cytotoxic T cells) and IL-2+ (activated T cells) in mammary tumor tissues of TM-F3 when compared to the TM group." (PMID 35972917, 2022). "To address our research question, we used the anti-HER2 antibody trastuzumab and determined the cytotoxic potential of IL-2-activated, donor-derived NK cells in breast cancer models in the presence of hypoxia, an immunosuppressive factor frequently present in solid tumors." (PMID 34203549, 2021). "Here, we report that the IL-2-activated NK cell also remained functional against breast cancer." (PMID 34203549, 2021). "ICIs and interleukin-2 (IL-2) by conjugation (for antibodies) or recombinant fusion (for cytokine) to the von Willebrand factor A3 domain (a collagen-binding domain) eradicated tumors and exhibited obvious safety and efficacy in a breast cancer model." (PMID 34733848, 2021). "Herein we demonstrate that isomaltosoide, an iron formulation used for correction of iron deficiency in humans, negatively impacts on the efficacy of cancer immunotherapy and combined IL-2/doxorubicin chemo-immunotherapy in a murine E0771 mammary carcinoma model." (PMID 33344239, 2020). "Herein, we analyzed the effects of intravenous iron supplementation on T cell function and on the effectiveness of anti-cancer chemotherapy with IL-2/doxorubicin or immunotherapy with checkpoint-inhibitor anti-PD-L1 in C57Bl/6N female mice with implanted E0771 mammary carcinomas." (PMID 33344239, 2020). "The aberrant production of IL-2 has been documented in several tumors, including breast cancer." (PMID 32850353, 2020). "In line with this, an in vitro study in breast cancer suggested that the combination with IL-2 or IL-15 could boost the lytic activity against tumor cells, therefore augmenting the therapeutic efficacy of Avelumab." (PMID 33266177, 2020). "Since PyMT tumors that overexpress IL-31 exhibit an increase in IL-2 concentrations, we investigated whether there is a correlation between its expression and IL-31 or IL-31Ra in breast carcinoma biopsies from patients." (PMID 32843492, 2020). "In addition, we found that GR-high breast cancers have a higher immune response with higher IL-2 pathway and apoptosis and lower proliferation, explaining improved survival." (PMID 32629782, 2020). "And the chloroform ethanol extract of XHP could increase the expression of IL-2 in Walker 256 breast cancer cells, reduce expression of IL-10, and improve the proportion of T lymphocytes, thus playing antitumor effect." (PMID 29849718, 2018). "Similar results were obtained when incubating breast cancer cells with IL-2." (PMID 29350274, 2018).
breast carcinoma (continued). "Overexpression of IL-2 and its receptor chains (α, β, and γ) is correlated with breast cancer development and may also be related to the tumour malignancy." (PMID 29685151, 2018). "The production of IL-2 was first connected to breast cancer progression in patients treated for breast cancer who had a relapse percentage of 4.7% if the IL-2 plasmatic level was normal while the relapse percentage increased to 33.3% if IL-2 was low after a 10-12 month follow-up." (PMID 30648081, 2018). "Furthermore, zoledronate with low dose of IL-2 have also been tested in treating prostate cancer and advanced breast cancer where partial remissions haves been reported." (PMID 28894450, 2017). "In published reports of in vitro γδTc cytotoxicity against breast cancer cell lines, it is unclear whether IL-2 was included in the assays." (PMID 28713391, 2017). "Similarly, Tai chi increased IL-6 and decreased IL-2 levels which was positively related to an improvement in QoL in breast cancer patients." (PMID 26498685, 2015). "TCC practice in breast cancer survivors significantly enhanced functional capacity and health-related life quality, decreased fat mass with increased IL-6 and decreased IL-2 levels, and maintained insulin level compared to the breast cancer survivors only receiving psychosocial support." (PMID 25653009, 2015). "Moreover, MK aqueous extract has delayed the formation of breast cancer and reduced the mitotic division of the tumor through stimulation of T cell cytokine production (IL-2 and IFN-γ) and cytotoxicity." (PMID 26335427, 2015). "This might be achieved for instance by stimulating γδ T cells in these patients through injection of zoledronate and IL-2, as recently performed by our group in prostate and breast cancer." (PMID 23189169, 2012). "Our pilot study demonstrates the feasibility, safety and tolerability of Her2-pDNA vaccination in combination with GM-CSF and IL-2 in a small number of advanced breast cancer patients who are on concurrent trastuzumab treatment with findings warranting further exploration of this concept." (PMID 20529245, 2010). "Previous in vitro and in vivo studies have shown that cytokines such as IL-2, IL-12, IL-15 and interferon can enhance the effect of antibody-ADCC for immunotherapy of cancer, e.g., IL-2 and IL-15 enhanced NK cell response to Herceptin-coated Her2/neu+ breast cancer cells in vitro." (PMID 20939894, 2010). "TIL isolated from human solid tumours of different types, including breast carcinoma, have demonstrated poor proliferative responses to mitogens in-vitro which recovers after several days co-culture with interleukin-2 (IL-2), or after culture with antigen presenting cells (APC)." (PMID 11870535, 2002). "Consequently, active immune stimulation with a beta-interferon interleukin-2 sequence could stimulate the effector immune cells to attack breast cancer cells." (PMID 38332913, 2023). "To test whether we would see better outcomes in tumors that express higher levels of EIIIB + FN, we also tested the anti-EIIIB IL-2 fusions i.v. as a monotherapy in the 4T1 orthotopic breast cancer model, which has been shown to express more EIIIB than the B16F10 model." (PMID 36712341, 2022). "Thus, among the pro-inflammatory cytokines in breast cancer, the content of IL-1β, IL-2, and IL-6 increased (+16.1%, +25.0%, and +12.7%, respectively), while for TNF-α, MCP-1, IL-8, and IL-18, the content decreased (−36.2%, −23.8%, −15.0%, and −12.1%, respectively)." (PMID 36286034, 2022). "In patients with breast cancer who were not receiving chemotherapy, inverse associations were observed between most proinflammatory and anti-inflammatory cytokines and depression severity, especially IL-2 (regression coefficient = − 1.20)." (PMID 32703187, 2020).
breast carcinoma (continued). "Indeed, repeated administration of zoledronate and IL-2 in the patients with breast cancer and RCC could inhibit the proliferative capacity of Vγ9Vδ2-T cells and reduced the responsiveness of Vγ9Vδ2-T cells to re-stimulation." (PMID 28894450, 2017). "Furthermore, TNF-α, IL2, and IL1b have not been associated with fatigue and RT in breast cancer and other malignancies." (PMID 24800238, 2014). "In a randomized controlled trial (KCT0000939), desflurane was found to be beneficial to the immune response by maintaining the IL-2/IL-4 and CD4+/CD8+ T-cell ratios in breast cancer patients, providing an immune protective response." (PMID 40584290, 2025). "We focused on IL-2, IL-6, IL-10, and TNF-α due to their well-documented relevance in breast cancer immunobiology, as reported in previous studies." (PMID 40869161, 2025). "In breast cancer patients, serum IL-12 levels increased after mistletoe therapy, and peripheral blood mononuclear cells showed increased production of IFN-γ and IL-2." (PMID 40369535, 2025). "Obesity has little effect on mammary tumor incidence in rodents before OVX, but after OVX, obesity leads to more tumors and reduced anti-inflammatory cytokines (IL-2, IL-4)." (PMID 40584290, 2025). "These tmTNF-α-specific CAR-T cells demonstrated strong cytotoxicity against tmTNF-α-positive breast cancer cells in vitro and in vivo, accompanied by the increased secretion of IFN-γ and IL-2." (PMID 39596267, 2024). "The results of Meng’s meta-analysis showed a significant reduction in IL-2, IFN-γ, IL-6, IL-1β, and TNF-α levels in breast cancer patients participating in the Qigong practice group." (PMID 36831519, 2023). "In an orthotopic mammary tumor model, CD8 + T cells displayed increased production of granzyme B, IL-2, and TNF-a at higher doses of CIRT while high-dose photon therapy did not induce secretion of these cytokines from CD8 + tumor-infiltrating lymphocytes." (PMID 36138265, 2023). "For example, F16 and P12 antibodies specific to the alternatively spliced domains of the large isoform of TN-C, have been fused with IL-2 to promote CD45+ immune cell recruitment and tested in a xenograft model of human breast cancer." (PMID 36338519, 2022). "Another study also described enhanced antitumor activity of the T cells after treatment of mouse model of breast cancer with naringenin, with an increased proportion of IFN-γ and IL-2 expressing T cells." (PMID 35606804, 2022). "In the 4T1 breast cancer model, a higher frequency of CD4+ and CD8+ T cells producing IFNγ, TNFα, or IL-2 was found in mice treated with T. usneoides." (PMID 36358804, 2022). "To confirm these results, we performed a similar analysis using a human breast cancer specimen, cut into pieces, engineered in ALTEN and randomized prior to IL2 or vehicle exposure." (PMID 35611998, 2022). "Some studies have shown that in the breast cancer model mice, the HS group can significantly increase the tumor inhibition rate, serum INF–γ and IL-2 levels, and decrease serum TNF-α level." (PMID 35707465, 2022). "Immunohistochemistry (IHC) analysis of immune cell populations (CD4, CD8 and CD68), cytokine (IL-2) and surface proteins (MHC class I and class II) were carried out to quantify their expression in mammary tumor tissues." (PMID 35972917, 2022). "A manifold of cytokines including IL-2, IL-6, IL-8 or IFN-γ have been described to be secreted by breast cancer cells." (PMID 33538861, 2021). "We next examined the function of the CAR T cells transduced with each of the promoter constructs, measuring cytokine release (IL-2 and IFN-γ), cytotoxicity and activation following incubation of CAR T cells with the Her2+ MCF-7 breast cancer cell line." (PMID 32706785, 2020). "Almost 60% (13 out of 22) of patients with advanced breast cancer had delayed disease progression when bispecific antibodies for HER2 and CD3 were combined with IL-2 and granulocyte monocyte colony stimulating factor (GM-CSF) in a Phase I clinical trial." (PMID 31366131, 2019).
breast carcinoma (continued). "Inflammatory cytokines including interleukins (IL-1β, IL-2, IL-6, IL-8, IL-12), tumor necrosis factor alpha (TNF-α), and interferon gamma (IFN-γ) are key inflammatory mediators of interest in breast cancer progression." (PMID 26970739, 2016). "T-lymphocytes obtained from draining lymph nodes of 4T1 (murine breast cancer cell) sensitized BALB/C mice were activated in-vitro with Bryostatin/Ionomycin for 18 hours, and were grown in the presence of Interleukin-2 for 6 days." (PMID 25334026, 2014). "Interleukin 2 (IL-2) and interferon-γ (IFN-γ) have been demonstrated in animal models of breast cancer to be important in preventing metastasis." (PMID 23434903, 2013). "It was previously shown that in the murine mammary carcinoma model, deletion of Tregs resulted in increasing numbers of IFN-γ and IL-2-producing CD4+ T cells at tumor sites." (PMID 22890822, 2013). "The study was phase I/II clinical trial of cancer vaccine composed with autologous HSC-derived DC and IL-2 performed on six RCC and four breast cancer patients." (PMID 22013914, 2011). "The CD3+ T cells isolated from PBMCs of breast cancer patients were cocultured with CHO/IDO and CHO/EGFP cells in complete medium supplemented with 10% FBS and 50 U/ml IL-2 for 7 days." (PMID 22110525, 2011). "Our anti-tumor vaccine with DC and IL-2 was tolerable and induced the antigen-specific cellular immunity in the metastatic RCC and Breast cancer patients." (PMID 22013914, 2011). "Specifically, IL12, IL2 and IFNG, all involved in Th1 mediated immune response, showed strong correlations in both ER+ and ER- breast cancer, while IL13 (involved in a Th2 immune response) was generally anti-correlated to these pathways." (PMID 21050467, 2010). "Similarly, our findings suggest that increased randomness in the patterns of expression of the IL2 pathway, a well-known tumour suppressor pathway mediating tumour inhibition through formation of natural killer cells, is a critical determinant of breast cancer metastasis." (PMID 20673354, 2010). "Since oestrogens not only affect breast cancer but also have been shown to modulate immune function and secretion of immune-regulatory cytokines, we explored whether administration of oestradiol altered the immune response induced by an adenoviral vector expressing B7-1/IL-2." (PMID 12865933, 2003). "Conversely, an independent case–control study observed significantly lower levels of circulating IL-4 in breast cancer patients, while IL-2 did not significantly differ from those of the controls." (PMID 41150099, 2025). "Whereas, breast cancer cells exposed to RT alone displayed an augmentation in TGF-β, VEGF, INF-γ, IL-2, and IL-6 levels by 31, 45.5, 36.5, 51, and 88.6%, respectively, for MCF-7 cells, and by 27.1, 28.5, 68.6, 136, and 124.2%, respectively, for MDA cells when compared with Amy-F group." (PMID 37210478, 2023). "In breast cancer, ER, PR, and HER2 status have been verified as important prognostic factors; therefore, based on these different statuses, we also investigated how the expression of IL-2 and IL-17 influenced patient survival." (PMID 35493488, 2022). "Consequently, in vivo elimination of CAFs in a murine model of breast cancer using a vaccine targeting FAP can shift CD4+ T cell polarization from a Th2 to a Th1, increase expression of IL-2, increase CD8+ T cell functions, and hamper Tregs recruitment." (PMID 36338519, 2022). "The toxicity of human lymphocytes against MCF-7 breast cancer cells was assessed by using a pectin guar gum zinc oxide nanocomposite, finding it increased IFN-γ, interleukin 2 (IL-2), and TNF-α cytokine release, CD3, CD8, and CD56 expression, and cancer cell mortality." (PMID 36364232, 2022). "They showed anticarcinogenic effects in breast tumors, mainly by ameliorating some pro-inflammatory cytokines IL-17, IL-2, IL-12, IFN-γ, and TNF-α, in addition to improving DTH and NK responses, decreased tumor volume, and prolonged survival in breast cancer animal model." (PMID 36290639, 2022).